OR2D2 (olfactory receptor family 2 subfamily D member 2)
Description:
Odorant receptor.
Synonyms: OR11-610; OR2D1; hg27
Tractability: Antibody: UniProt places it where antibodies can reach, with medium confidence; UniProt predicts a signal peptide or a membrane-spanning region; its Gene Ontology location is reachable by antibodies, with medium confidence.
Gene: Protein-coding gene on chromosome 11 (6,891,574 to 6,892,500, reverse strand). Ensembl gene ENSG00000166368.
Subcellular location: Cell membrane
Pathways (Reactome):
Sensory Perception: Expression and translocation of olfactory receptors
Gene Ontology:
Molecular function: olfactory receptor activity; G protein-coupled receptor activity
Biological process: detection of chemical stimulus involved in sensory perception of smell; sensory perception of smell; G protein-coupled receptor signaling pathway
Cellular component: membrane; plasma membrane
Genetic constraint (gnomAD): Loss-of-function variants: 20 observed, 16.86 expected, observed/expected ratio (o/e) 1.19, 90% interval 0.83 to 1.7. The upper end of that interval is the gene's LOEUF score, 1.7, which puts it in group 6 of 6, group 1 being the genes least tolerant of losing a copy. Missense variants: 409 observed, 390.31 expected, observed/expected ratio (o/e) 1.05, 90% interval 0.97 to 1.14. Synonymous variants: 164 observed, 152.83 expected, observed/expected ratio (o/e) 1.07, 90% interval 0.94 to 1.22.
Homologues: Orthologues: dog OR2D2 (86% identical), mouse Or2d2 (85% identical), mouse Or2d2b (84% identical), rat Or2d2 (84% identical), pig OR2D2 (83% identical), rat Or2d2b (83% identical), macaque OR2D2 (81% identical). Paralogues in human: OR2D3 (64% identical), OR2B2 (51% identical), OR2B6 (51% identical), OR2F1 (51% identical), OR2F2 (50% identical), OR2B3 (49% identical), OR2G6 (48% identical), OR10A7 (48% identical), OR10C1 (48% identical), OR13C4 (47% identical), OR2G3 (47% identical), OR13C3 (47% identical), and 80 more.